CD4 (CD4 molecule)
Diseases named in the same sentence as CD4 in open-access papers (continued):
Sharing a sentence is not in itself a finding about the gene and the disease.
tumor (continued). "In addition, UDP-treated tumors showed a higher presence of MHCIIhi tumor-associated macrophage (TAM) and of CD3+CD8+ and CD3+CD4+ tumor-infiltrating T-lymphocytes (TILs), both markers of anti-tumor immune response." (PMID 34604232, 2021). "A more recent study comparing pre-treatment and biopsy material obtained from rectal tumours 7 days after irradiation showed that a high density of CD4+ and FoxP3+ cells pre-treatment was significantly associated with tumour shrinkage, and that this link was most pronounced in the 7 day biopsies." (PMID 34321074, 2021). "The immune cells analyzed included CD8+ T cells, CD4+ T cells, B cells, tumor-associated macrophages (TAMs), monocytes, M1 and M2 macrophages, cancer-associated fibroblasts (CAFs), myeloid-derived suppressor cells (MDSCs), neutrophils, DCs, and natural killer (NK) cells." (PMID 34777336, 2021). "Whether TLS-associated DCs present tumor antigens directly to CD8+ T cells or whether CD4+ Th cells participate in the production of CD8+ cytotoxic T cell responses in TLSs remains to be further studied." (PMID 34394083, 2021). "The gene markers of immune cells were used to analyze and identify the immune cells, including CD8+ T cells, CD4+ T cells, regulatory T cells, B cells, tumor-associated macrophages (TAMs), M1 and M2 macrophages, monocytes, neutrophils, DCs, and natural killer (NK) cells." (PMID 35222518, 2021). "For example, SPP1 encoding osteopontin (OPN) and VTCN1 (aka B7-H4) are the genes known to be involved in cytokine production and negative regulation of T cell mediated immunity, suggesting a deficiency in T cell-mediated immunity in tumor associated CD4+ T cells." (PMID 34012510, 2021). "In addition, the expression of MHC class II molecules, such as HLA-DR, in tumor tissue has been linked to the presence of tumor-infiltrating lymphocytes (TILs) and high expression of CD4, CD3D, and CD8A." (PMID 34439290, 2021). "We found that high-risk-score LUAD patients had higher proportions of activated CD4 memory T cells, resting NK cells, M0 macrophages, M1 macrophages, and activated mast cells, confirming that the risk model had a regulatory effect on tumor microenvironments." (PMID 34540825, 2021). "Abundance of tumor-infiltrating lymphocyte (i.e., activated CD4+/CD8+ T cells, etc.)was significantly associated with the condition of antitumor immunity, suggesting that ICI cluster C could be regarded as inflamed tumors." (PMID 34512634, 2021). "Extracellular ATP works through P2Rs to trigger recruitment and activation of various immune cells, including CD8+ and CD4 + T cells, Tregs, tumor-associated macrophages (TAMs), myeloid-derived suppressor cells (MDSCs), neutrophils, macrophages, and dendritic cells (DCs)." (PMID 34796785, 2021). "Despite the evidence showing that the accumulation of Th1 and Th17 cells promotes NASH, other studies suggest that dysregulation of lipid metabolism during NAFL and NASH causes a selective loss of CD4 T cells that leads to impaired anti-tumor surveillance in mouse models and human samples." (PMID 34777255, 2021). "Furthermore, B cells activated by transgenic LMP1 expression were able to elicit tumor-associated, antigen-specific CD4+ and CD8+ T cells in a mouse model." (PMID 35053187, 2021). "Tumor cells in MF are classically CD3+CD4+CD8−, with frequent loss of CD7." (PMID 34118946, 2021). "Furthermore, they showed that TNBC progression was accompanied with decreased proportion of stromal tumor-infiltrating lymphocytes (TILs) including B cell, CD4+ naive T cell, CD8+ T cells and cancer-associated fibroblasts in metastatic TNBCs." (PMID 34659647, 2021). "Tregs represent a minor CD4+-T cell population, maintaining immune homeostasis by inhibiting effector T cells, being increased in nearly all cancers associating with metastasis, tumor recurrence, and treatment resistance." (PMID 34337083, 2021).
tumor (continued). "Interestingly, these cells appeared to be spatially located close to HRS tumor cells with loss of MHC-II, a likely key mechanism of evasion of anti-tumor CD4+ effector T-cells in cHL." (PMID 34068762, 2021). "It is worth noticing that the underlying anti-tumor mechanism of cytotoxic CD4+ GZMB+ T cells may be different in pMMR CRC." (PMID 34631551, 2021). "However, these TFH cells secrete significantly less IL-21 than other circulating CD4+ T cells and associate with decreased serum IL-21 levels, suggesting a severe limitation of the expected anti-tumour functions of TFH cells in DLBCL (right)." (PMID 34572910, 2021). "The combination of GLP-Au and doxorubicin could strongly inhibit the tumor growth and lung metastasis of 4T1, restore the weight loss caused by doxorubicin, and increase the percentage of memory T cells in CD4+/CD44+." (PMID 33935714, 2021). "Furthermore, NSUN4 had the strongest correlation with CD4+T cells and tumor-associated neutrophils, which is consistent with the results shown in previous studies." (PMID 34195072, 2021). "Furthermore, against tumors that do not express MHC class II or have mutated defects, APC uptake of tumor-associated antigens is crucial for an effective CD4+ T helper response." (PMID 34514097, 2021). "Interestingly these findings were confirmed in B2M low-expressing MMRd tumor patients, whereby the response to anti PD-1 was associated with high number of tumor infiltrated CD4+ T cells." (PMID 34072037, 2021). "Recently, PD-L2 expression was identified as a promising prognostic biomarker and noted to associate with low tumor-infiltrating immune cells (including CD4 + ); however, the cellular phenotype and the spatial discrimination between intra- and perifollicular localization were not investigated." (PMID 34267181, 2021). "We discovered that the low-risk group was related to more TIICs such as CD8+ T cells, CD4+ T cells, B cells, and neutrophils, whereas the high-risk group was related to more tumor-infiltrating immune cells such as NK cells, macrophages, and T cell regulatory (Tregs)." (PMID 34610581, 2021). "Furthermore, high levels of CD4+ T-cells in the tumor microenvironment were associated with M. franklinii presences." (PMID 34573440, 2021). "One could envision that modulating CD4-TCR-MHC topologies could in a similar manner enhance T cell responses to rare self-like tumor-associated antigens (TAA)." (PMID 34012443, 2021). "Tumor implantation caused a dramatic increase in pulmonary CD4+CD25+Foxp3+ Tregs 21 days later, and this increase was unaffected by treatment with BEMPEG (3.1% ± 0.8, 3.1% ± 0.9 and 0.8% ± 0.1 of live cells for vehicle, BEMPEG and no tumor groups, respectively)." (PMID 33152115, 2021). "The results revealed that the risk score was moderately correlated with all the CD4+T cells and weakly associated with other five tumor-infiltrating immune cell subtypes, including B cells, CD8+T cells, macrophages, neutrophils, and dendritic cells (both p < 0.05)." (PMID 33194633, 2020). "Moreover, miR-155 is essential for the development of MDSC and also for MDSC-mediated modulation of CD4+Foxp3+ regulatory T cells, indicating that MDSCs are associated with miR-155 to promote tumor growth." (PMID 33133086, 2020). "In addition, blocking the binding of CD40/CD40L between Bregs and CD4+ T cells in two different tumor models caused distinct immune responses in terms of Th1/Th2 differentiation and Treg induction." (PMID 33193391, 2020). "Although we have not yet identified an EBV-specific molecular and immunologic mechanism by which PD-1 blockade may have affected the CD4+ Tregs function, some correlations exist with neoplasias caused by EBV." (PMID 33511078, 2020).
tumor (continued). "The ICOS-driven interaction between tumor associated CD4+ T cells and ICOSL-expressing TA-pDCs sustain the expansion of ICOS+ FoxP3+ Tregs in the tumor microenvironment and promote the secretion of IL-10 and TGF-β from Tregs, which support an immunosuppressive microenvironment and tumor progression." (PMID 32054102, 2020). "Moreover, VISTA expression was higher in CD68+ tumor-associated macrophages (TAMs; 32.58%) than in CD4+ T cells (4.97%), CD8+ cytotoxic T cells (4.48%), or CD20+ B cells (1.46%)." (PMID 33250890, 2020). "In the immunosuppressive TME, particularly in T-cell inflamed tumours, several types of tumour-promoting cells are present, such as CD4+ regulatory FoxP3+ T-cells, tumour-associated macrophages, myeloid-derived suppressor cells, and infiltrating cytotoxic CD8+ T-cells." (PMID 33121210, 2020). "Results suggest that tumor‐associated DPT cells may derive from infiltrating CD4+ or CD8+ single positive T (SPT) cells." (PMID 32670760, 2020). "Tumor-infiltrating immune cells include NK cells, monocytes, CD8+ cytotoxic (memory) T cells, CD4+ helper (Th1, Th2) T cells, regulatory T cell (Treg), B-cells, tumor-associated macrophages (TAMs), tumor-associated neutrophils (TANs), myeloid-derived suppressor cells (MDSCs), DCs, and NK cells." (PMID 32992948, 2020). "We next interrogated whether CD4+ T cell subtypes were altered by drug administration, as these cells have been implicated as important regulators of both pro and anti-tumor immunity." (PMID 32300202, 2020). "At D16 post tumor implantation, using flow cytometry analysis, we found that the deficiency of Bcl6 results in an impairment of Treg cells, evidenced by the decreased proportion and absolute number of Foxp3+CD4+ T cells." (PMID 32477338, 2020). "Clinically, the tumor-infiltrating levels of cytotoxic CD4 cell, Mucosal associated invariant T (MAIT) cell, and exhausted CD8+ T cell might be used as predictors for vascular invasion, recurrence, and overall survival." (PMID 33133170, 2020). "A decreased expression of CD4+ cells is usually present, causing immune escape of tumor cells." (PMID 32050977, 2020). "Alternatively, chemotherapy-induced cell death could cause the release of tumor antigens and cause the activation of CD4 T cells specific for these antigens." (PMID 32630460, 2020). "For tumor therapy, nucleic acid-based vaccines need to encode tumor-specific immunogenic peptides, which allows to comprise antigen-encoding sequences of different proteins within one minigene aimed to activate a broader number of CD4+ and CD8+ T cells." (PMID 32917034, 2020). "Similarly, in the AT3 model, NAM treatment was associated with increased tumor infiltration by CD4+ T cells expressing TNF alone, TNF and IFNG, as well as TNF, IFNG, and IL2." (PMID 32732875, 2020). "Differently, tumor CD4+ T cells were principally associated with translational regulation (“Regulation of eIF4 and p70S6K Signaling” pathway), activation of the Inositol phosphate pathway, and signaling mediated by glucorticoids; highlighting intrinsic differences with the lymph node residing cells." (PMID 32601304, 2020). "The IMMO-GLIO-01 glioma clinical trial published a case study of a 53-year old women with GBM in which longitudinal monitoring of her immune response during the treatment regimen, noted that a shift of the CD4:CD8 ratio was associated with magnetic resonance imaging (MRI) tumor progression." (PMID 32240177, 2020). "Strikingly, tumors of mice treated with the G100–ACT combination had drastically lower percentage of CD8− CD4− cells, a population of cells that have been previously identified as “defective tumor-associated T cells,” whose presence is associated with tumor progression." (PMID 32579133, 2020).
tumor (continued). "Systemic administration of a P2X7R antagonist to tumor-bearing WT mice reduces tumor growth and upsets the immune infiltrate causing on one hand an increase in CD4+ and Teff cells, and on the other a down-modulation of both NTPDase1/CD39 and NT5E/CD73 expressed by CD8+ Treg cells." (PMID 33613285, 2020). "Importantly, its role in tumour-associated dendritic cells for the presentation of tumour antigen to CD4+ lymphocytes, and its role in anti-tumour immune responses were demonstrated." (PMID 32825056, 2020). "In contrast, while NK cells seemed to play no significant role in the anti-tumor activity, CD4+ T cells functional blockade caused a drastic decrease in tumor growth that could be attributed to CD4+ Treg cell depletion." (PMID 33126649, 2020). "Reduction of 50% of Treg cells resulted in a better prognostic value by a significant reduction in the tumor load, which was associated with an increased percentage of both CD4+ and CD8+ T-activated cells in MLN in CAC mice receiving immunotherapy with the monoclonal antibody PC61." (PMID 32674255, 2020). "For instance, CD4+CD25hi Tregs and tumor-derived γδ Tregs cause DNA damage-associated senescence in effector T cells through nutrient competition, resulting in the activation of a senescence signaling network involving ATM, MAPKs (ERK1/2 and p38 MAPK), and STAT1/3 protein." (PMID 32570952, 2020). "In the tumor niche, GBM cells release attractant factors to recruit endothelial cells (angiogenesis) and immunocytes, including glioma-associated microglia/macrophages and tumor-infiltrating lymphocytes (ie, CD4+ T cells, CD8+ T cells, natural killer [NK] cells, and regulatory T cells [Tregs])." (PMID 33205044, 2020). "To examine whether antitumor effect of GLP was associated with its immunological enhancement in tumor-bearing mice, we analyzed the proportion of CD4+ and CD8+ T cells as well as the level of IFN-γ and IL-12 in spleens from mice." (PMID 32530032, 2020). "However, tumor-infiltrating CD4+ and CD8+ T-cells are associated with varying patient survival and clinical outcomes in many types of cancer such as breast, colorectal, and lung cancers." (PMID 32635472, 2020). "However, there were also instances in which CD8/CD4 ratio was not linked to clinical outcomes, and some researchers even reported that a high CD8/CD4 ratio was associated with alcohol use and poor tumour differentiation." (PMID 32758195, 2020). "Lenvatinib may decrease tumor-associated macrophages, facilitate polarization from an M2-like phenotype toward an M1-like phenotype, and enhance CD4+ and CD8+ T-cell tumor infiltration, while sorafenib may have the opposite effects." (PMID 32722224, 2020). "The affinity of CTLA4apt (aptamer to CTLA4) to STAT3 small interfering RNA (CTLA4apt-STAT3 siRNA) may sharply decrease the number of tumor-associated CD4+ regulatory Tregs." (PMID 33050544, 2020). "However, the use of CD4 T cells in ACT should also circumvent one of the common tumour escape mechanisms, which is the loss of MHC class I to prevent recognition by the immune system." (PMID 31915853, 2020). "Moreover, Klf4, characterized as a novel tumor suppressor in multiple tumor types, is significantly decreased, indicating that CD4 TCM cells are susceptible to cell death in aged mice." (PMID 33644036, 2020). "The metabolic dysfunctionality observed in the CD38 expressing tumor-infiltrating CD4 T cells could also be mediated by the loss of anti-oxidant potential of T cells." (PMID 32709019, 2020). "IL-6 sustains tumor survival, but it also drives production of senescent cells that exhibit a senescence-associated secretory phenotype, all of which are predicted to augment dysfunction in CD4+ and CD8+ T cells." (PMID 33013907, 2020). "Furthermore, VISTA expression was higher in CD68+ tumor-associated macrophages (TAMs) than in CD4+ T cells, CD8+ cytotoxic T cells or CD20+ B cells." (PMID 33250890, 2020).
tumor (continued). "Next, it was examined whether YAP-deficient CD8+ cells contribute to the very strong anti-tumor immunity that YAP CD4 Cre mice exhibit using an adoptive transfer model." (PMID 32322254, 2020). "On the contrary, no conclusive results have been achieved on the prognostic impact of CD4+ TILs in NSCLC and, among the CD4+ subsets, Th1 lymphocytes have been associated with improved survival, while Th2 lymphocytes have been associated with tumor progression." (PMID 32365882, 2020). "Interestingly, inhibiting P2X7 with a selective antagonist like A740003 causes an increase in the percentage of infiltrating CD4+ cells and a significant drop in tumor weight and Treg abundance." (PMID 33841132, 2020). "Moreover, HSP90s gene expression in BRAC showed correlations with the infiltration of CD8+ T cells, neutrophils, macrophages, and dendritic cells (DCs), as well as the activation of tumor-associated macrophages (TAMs), DCs, and CD4+ helper T (Th) cells." (PMID 33145341, 2020). "In addition, type I IFN can activate DCs and CD8+ T cells, and promote the development of CD4+Th1, which is necessary for radiation therapy to cause an anti-tumor immune response." (PMID 32960261, 2020). "Additionally, CD4+ T cells showed the ability to specifically recognize tumor associated neo-antigens and are able to facilitate cancer clearance and reshape the tumor microenvironment." (PMID 32708265, 2020). "Tumor-infiltrating CD4+ T cells were also associated with better prognosis of NSCLC patients." (PMID 33193873, 2020). "The inhibitory activity did not require a direct cell-to-cell contact, but was mediated by cytokine secretion by tumor cells (IL-15 in particular) that caused a de novo functional differentiation of lymphocytes towards a T-regulatory immunophenotype (FOXP3+ CD4+ T-cells)." (PMID 31383005, 2019). "The authors observed that FMT from responding patients but not from non-responding patients into GF mice caused tumor growth delay, accumulation of CXCR3+CD4+ T cells in the tumor microenvironment, and up-regulation of PD-L1 in splenic T cells after PD-1 blockade." (PMID 31533218, 2019). "We then investigated whether OVA-specific CD4+ Th1 cells would promote differentiation of tumor associated macrophages also in vivo." (PMID 30853959, 2019). "However, the precise mechanisms underlying CD4+ T cell differentiation and functions in the tumor microenvironment are not completely understood." (PMID 31300052, 2019). "It is also associated with tumor, cancer, and CD4+ and CD8+ T cells." (PMID 31533276, 2019). "Resting memory CD4+ T cells were associated with a smaller tumor size." (PMID 31762828, 2019). "These immunomodulatory cytokines are also responsible for an increase in the T cell subsets, orchestrating phenotypic shifts in the CD4 T cell subtypes, and play a role in the increasing cytotoxic T cell activity in the tumor microenvironment of CD47 deficient tumors." (PMID 31882679, 2019). "Indeed, when CD4 T cell infiltration was stratified by gC1qR expression, the combination of high CD4 T cell infiltration and high tumor gC1qR expression was associated with significantly better overall survival compared to other combinations." (PMID 31681580, 2019). "More recent advances have been associated with individualized vaccines using tumor whole exome sequencing to identify autologous neoantigens, which have been shown to be immunogenic for intratumoral CD4+ and CD8+ T cell responses in early phase clinical trials in glioblastoma." (PMID 31552045, 2019). "However, to our knowledge, no results have been published so far that focused on the cognate interaction between tumor-associated macrophages and CD4+ Th1 cells in a wildtype in vivo situation." (PMID 30853959, 2019).